CEMIP (cell migration inducing hyaluronidase 1)
Diseases named in the same sentence as CEMIP in open-access papers (continued):
Sharing a sentence is not in itself a finding about the gene and the disease.
Cognitive impairment (1 paper, 2024). Abnormal cognition is characterized by deficits in thinking, reasoning, or remembering. "Further studies to better understand the cognitive impairment found in Cemip −/− mice showed decreased neurons in the dentate gyrus and decreased dendritic spine density that was accompanied by HA accumulation, suggesting HA degradation by CEMIP is important for synaptic formation." (PMID 39056785, 2024).
demyelinating disease (1 paper, 2024). A broad group of disorders that affect the myelin sheaths that cover the neurons. "Elevated expression of one such hyaluronidase, the Cell Migration Inducing and hyaluronan binding Protein (CEMIP), has been implicated in the pathogenesis and progression of several cancers as well as demyelinating diseases in the central nervous system (CNS)." (PMID 39454959, 2024). "Here, we have found that each of the three compounds we tested increased OPC differentiation at a greater rate than S3 at similar as well as lower concentrations, suggesting that these agents have the potential to be developed for therapeutics that target CEMIP activity in demyelinating diseases." (PMID 39454959, 2024). "Altogether, these data confirm that agents that can block CEMIP activity are capable of promoting OPC maturation, and support the notion that CEMIP inhibitors have the potential to be used to promote OPC maturation and remyelination in demyelinating diseases." (PMID 39454959, 2024).
disc degeneration (1 paper, 2025). "In the IDD mice model, CEMIP‐deficient mice exhibit higher expression of anabolic factors and signs of mitigated disc degeneration." (PMID 40400122, 2025). "By unraveling the relationship between CEMIP and fibrosis within disc degeneration, we open the possibility of developing targeted treatments that address the underlying mechanisms of IDD progression." (PMID 40400122, 2025). "A significant positive correlation between plasma CEMIP levels and Pfirrmann grading of disc degeneration (R2 = .4206, p = .0005) was observed, further supporting its value in assessing IDD severity." (PMID 40400122, 2025).
infarcts (1 paper, 2025). "Notably, LTBP1 and CRIP1, along with C1QC and PRSS23 (linked to WMH and infarcts) and CEMIP and ELN (associated with WMH and microbleeds), showed strong co-localization with ThioS- positive vascular amyloid deposits, but not with parenchymal plaques." (PMID 41282800, 2025).
keloid (1 paper, 2024). An irregularly shaped, elevated mark on the skin caused by deposits of excessive amounts of collagen during wound healing. "With the purpose of investigating the role of CEMIP in keloid hyperplasia, CEMIP expression in keloid fibroblasts was initially assessed." (PMID 39481283, 2024).
medulloblastoma (1 paper, 2020). A malignant, invasive embryonal neoplasm arising from the cerebellum. "Regarding macrophages in SHH medulloblastomas, CEMIP expression was negatively correlated M0 (p = 0.002, r = −0.378) while positively correlated with M2 macrophages (p < 0.001, r = 0.437)." (PMID 32508873, 2020).
metastasis (1 paper, 2023). The spread or migration of cancer cells from one part of the body (where they first appeared) to another. "CEMIP is a cell migration-inducing and hyaluronan-binding protein recently associated with poor prognosis when overexpressed in lymph node metastasis." (PMID 37576552, 2023).
metastatic prostate carcinoma (1 paper, 2022). A carcinoma that arises from the prostate gland and has spread to other anatomic sites. "In conclusion, inhibiting CEMIP-mediated protective autophagy may provide a therapeutic strategy for metastatic prostate cancer (PCa)." (PMID 35013120, 2022).
myocardial infarction (1 paper, 2023). Gross necrosis of the myocardium, as a result of interruption of the blood supply to the area, as in coronary thrombosis. "First, the protein expression level of CEMIP was detected by Western blotting following myocardial infarction." (PMID 37313693, 2023).
renal fibrosis (1 paper, 2023). A final common manifestation of a wide variety of chronic kidney diseases characterized by glomerulosclerosis and tubulointerstitial fibrosis. "Anti‐CEMIP antibodies have also been found to inhibit renal fibrosis in obese patients by inhibiting the Wnt/β‐catenin pathway, and CEMIP inhibition inhibited fibroblast proliferation and differentiation." (PMID 37313693, 2023).
Salmonella Infections (1 paper, 2023). Infections with bacteria of the genus SALMONELLA. "Among the multiple genes detected in this study, EXFABP, S100A9/12, CEMIP, FKBP5, MAVS, FAM168B, HESX1, EMC6, and others were found as potential candidate gene and transcript (co-) factors for resistance to Salmonella infection." (PMID 36902251, 2023).
Stroke (1 paper, 2025). Sudden impairment of blood flow to a part of the brain due to occlusion or rupture of an artery to the brain. "It will be interesting to explore whether CEMIP is also elevated following stroke, and whether CEMIP or HYAL1 influences HA catabolism at different times following stroke." (PMID 41586378, 2025).
triple-negative breast carcinoma (1 paper, 2022). An invasive breast carcinoma which is negative for expression of estrogen receptor (ER), progesterone receptor (PR), and human epidermal growth factor receptor 2 (HER2). "In triple-negative breast cancer, the loss of H3K27me3 at the CEMIP promoter via H3K27me3 demethylase results in upregulated CEMIP expression." (PMID 36291875, 2022).
cancer (100 papers, 2011 to 2026). A tumor composed of atypical neoplastic, often pleomorphic cells that invade other tissues. "Cell migration inducing protein (CEMIP) is overexpressed in various cancers, and is associated with an aggressive phenotype." (PMID 40610532, 2025). "Most prominently, CEMIP expression in numerous types of cancer has been functionally linked to tumor progression, metastasis, and therapy resistance." (PMID 39851529, 2025). "CEMIP-mediated HA degradation has also been linked to cancer cell migration in a size-dependent manner, with 35 kDa HA promoting migration and invasion of cancer cells, while 117 kD HA exerts the opposite effect." (PMID 39851529, 2025). "Recent evidence has highlighted the significant role of CEMIP in different cancers, associating it with diverse pathological states." (PMID 38390387, 2024). "This review primarily focuses on delineating CEMIP’s role in human cancer and its association with the regulation of CEMIP expression." (PMID 38390387, 2024). "Researchers in oncology identified that KIAA1199 encodes a protein that induces the migration of cancer cells and named it cell migration-inducing protein (CEMIP)." (PMID 35456905, 2022). "As a potential marker of cancers, CEMIP can associate with several types of microRNAs to be a novel therapeutic target for cancer treatment." (PMID 36451490, 2022). "Cell migration inducing protein (CEMIP) has been linked to carcinogenesis in several types of cancers." (PMID 35957875, 2022). "We found that the main genetic alterations of CEMIP in various cancers were mutation, amplification, deep deletion, structural variant, and multiple alterations." (PMID 34966410, 2021). "In the present study, we performed expression analysis for CEMIP in different kinds of human cancers, particularly in BC, and assessed the association of CEMIP expression with the prognosis of patients with BC." (PMID 34966410, 2021). "The resistant cells also expressed CEMIP, a protein associated with cancer cell survival, migration and invasion." (PMID 29371980, 2017). "We and others recently identified KIAA1199 as a novel cancer cell migration-promoting gene, referred to now as Cell Migration Inducing Protein (CEMIP), and linked CEMIP's expression to the maintenance of a mesenchymal-like phenotype and metastatic potential." (PMID 26009875, 2015). "Studies have demonstrated that CEMIP is highly upregulated in various types of cancers and could be a valuable diagnostic and prognostic tool in assessing tumor progression." (PMID 38835051, 2024). "Moreover, CEMIP is implicated in the pathogenesis of several human cancers, including prostate, breast, and colorectal cancer." (PMID 38390387, 2024). "Also implicated in the Wnt pathway, as well as the VEGF pathway, CEMIP (formerly known as KIA1199) has emerged via immunohistochemical studies as a possible biomarker for a variety of cancers." (PMID 37895248, 2023). "CEMIP (cell migration-inducing and hyaluronan-binding protein) has been implicated in the pathogenesis of numerous diseases, including colorectal and other forms of cancer." (PMID 36291875, 2022). "However, recent studies have shown increased CEMIP expression in cancers is associated with poor patient survival and leads to increased proliferation, EMT, invasion and migration." (PMID 35177031, 2022). "However, although CEMIP upregulation is associated with promoting tumors in most cancers, CEMIP may be antineoplastic in specific cancers." (PMID 36451490, 2022). "Nevertheless, a number of observations suggest that CEMIP may also contribute to tumor growth and the process of cancer dissemination through its expression in tumor-associated stromal cells, which serve to shape a pro-tumorigenic and metastasis-promoting microenvironment." (PMID 36291875, 2022). "CEMIP’s role in cancer metastasis includes contributing to cancer cells’ ability to withstand cell death, such as by anoikis and hypoxia." (PMID 41596231, 2026).
cancer (continued). "TMEM2L, now known as cell migration-inducing and hyaluronan-binding protein (CEMIP), has been associated with cancer metastasis." (PMID 41596760, 2026). "The intricate regulatory network that governs CEMIP highlights its pivotal role within diverse cellular pathways involved in cancer." (PMID 38390387, 2024). "In essence, a nuanced comprehension of the multilayered transcriptional circuitry and post-transcriptional regulatory networks governing CEMIP expression holds promise in unveiling novel strategies to target this oncoprotein effectively in cancer therapeutics." (PMID 38390387, 2024). "Although CEMIP is elevated compared to other hyaluronidases in some cancer cells and in demyelinating lesions, it is possible that the inhibitors tested here can act by influencing the expression of multiple hyaluronidases or HA synthases." (PMID 39454959, 2024). "Many studies have now demonstrated that CEMIP expression is high in migrating cells and in multiple different cancer types, mostly of epithelial origin, with overexpression in many of these cancers associated with poor clinical outcome." (PMID 39056785, 2024). "CEMIP (cell migration inducing hyaluronan binding protein) emerges as a pivotal oncoprotein governing cancer advancement through diverse pathways." (PMID 38390387, 2024). "This review provides a comprehensive summary of CEMIP’s role in various cancers and explores how both transcriptional and post-transcriptional mechanisms control its expression." (PMID 38390387, 2024). "While CEMIP holds promise as a potential target for early cancer diagnosis and therapy, it intersects with immune checkpoint blockade (ICB) therapy, mediating tumor immune escape." (PMID 38390387, 2024). "Further exploration is warranted to identify additional microRNAs or RNA binding proteins that target CEMIP, especially for their role in cancer pathogenesis and metastasis." (PMID 38390387, 2024). "Numerous studies have highlighted the elevated levels of CEMIP in cancer cells and its connection to cancer metastasis through the Wnt/β-catenin signaling pathway." (PMID 38761291, 2024). "Studies have clarified that overexpressing CEMIP exerts the role of hyaluronidase, which makes the solid tumors loose, contributing to cancer cells escaping from the in situ tissue and achieving distal diffusion." (PMID 37662915, 2023). "Previous studies have also reported that the PI3K signaling pathway is closely related to the expression of CEMIP in various cancers." (PMID 37668818, 2023). "CEMIP silencing in MDA-MB-435 cancer cells leads to the transformation of mesenchymal cells into epithelial cells, thereby reducing the ability of cells to migrate in vitro." (PMID 36451490, 2022). "CEMIP has recently been shown to contribute to metastasis and invasion in a number of different cancers." (PMID 35177031, 2022). "Using the bioinformatic databases, we selected several neighboring genes that were related to CEMIP from Coexpedia to explore the potential molecular mechanisms of the role of CEMIP in cancer and other diseases." (PMID 35370456, 2022). "Since CEMIP has been found to catalyze the catabolism of hyaluronan, and was identified as therapeutic target of cancers through regulation of tumorigenesis, the role of CEMIP in PTC progression was then investigated." (PMID 35543351, 2022). "Overexpression is related to metastasis and poor prognosis of cancers that several CEMIP and tumors research detected." (PMID 36451490, 2022). "Using Oncomine, we first conducted an overall analysis of the expression of CEMIP in multiple cancers and diseases." (PMID 35370456, 2022). "To date, virtually all efforts aimed at understanding the tumor- and metastasis-promoting roles of CEMIP have focused on its function in cancer cells." (PMID 36291875, 2022). "In the MEXPRESS and UALCAN databases, the level of DNA methylation in CEMIP was higher in normal tissues than in cancer tissues." (PMID 35370456, 2022).
cancer (continued). "Based on these results, it is proposed that CEMIP correlates with cancer invasion and metastasis ability through the Wnt/β-catenin signaling pathway." (PMID 36451490, 2022). "We subsequently investigated the expression of CEMIP in BC, focusing on the differential expression between cancer and normal tissues." (PMID 35370456, 2022). "CEMIP, known as KIAA1199, was first described as an inner-ear-specific gene, which also played a role in developing and maintaining cancer metastasis." (PMID 35655258, 2022). "Oncomine analysis revealed that CEMIP expression was significantly higher in cancer tissues than in normal samples." (PMID 35370456, 2022). "Taken together, CEMIP represents an exciting new player in the progression of colorectal and other types of cancer that holds promise as a therapeutic target and biomarker." (PMID 36291875, 2022). "High expression of CEMIP in both carcinoma tissues and cells of papillary thyroid was verified in this study." (PMID 35543351, 2022). "Further highlighting its role in tumor metastasis, CEMIP has been implicated in EMT and increased cancer cell migration." (PMID 33809973, 2021). "After the downregulation of CEMIP, the number of apoptosis of cancer cells increased, suggesting that the overexpression of CEMIP promoted the chemoresistance of GC cells to 5-FU." (PMID 34338150, 2021). "Recent studies have demonstrated that the overexpression of CEMIP leads to tumor cell invasion, migration and carcinogenesis in many types of cancer." (PMID 33995632, 2021). "Next, the potentially genetic regulatory mechanisms of CEMIP, including DNA methylation, genetic alteration, and upstream transcription factors, were explored in BC and other cancers." (PMID 34966410, 2021). "Moreover, our findings suggested that CEMIP might exert its carcinogenic roles in the tumor microenvironment via participation in the extracellular matrix formation, increasing cancer-associated fibroblast (CAF), M2 macrophage, and neutrophil infiltration and decreasing CD8+ T cell infiltration." (PMID 34966410, 2021). "KIAA1199, also referred to as cell migration inducing protein (CEMIP), plays a role in the development and maintenance of cancer metastasis." (PMID 34233709, 2021). "All works above indicate that CEMIP plays an important role in the oncogenesis and progress of carcinomas, and the exact mechanism remains to be explored." (PMID 34966410, 2021). "Recently, several investigations have suggested that CEMIP is involved in the metastasis of numerous cancers, including GC." (PMID 32754443, 2020). "CEMIP (cell migration inducing protein) is a protein involved in migration of cancer cells and will be the subject of our future investigation." (PMID 32369931, 2020). "Establishing the link between CEMIP and increased cell survival in adverse environmental conditions via BiP increases our understanding of how cancers progress." (PMID 31303964, 2019). "CEMIP and BiP are overexpressed in cancers, where they contribute to cancer progression and metastasis." (PMID 31303964, 2019). "Several reports have characterized CEMIP as a key protein involved in cancer progression due to its ability to promote proliferation, migration, hyaluronic acid depolymerization, and epithelial-to-mesenchymal transition (EMT)." (PMID 31303964, 2019). "Cell migration-inducing protein (CEMIP) and binding immunoglobulin protein (BiP) are upregulated in human cancers, where they drive cancer progression and metastasis." (PMID 31303964, 2019). "CEMIP (for “Cell migration-inducing protein” also called KIAA1199 and Hybid for “Hyaluronan-binding protein”) expression is increased in cancers and described as a regulator of cell survival, growth and invasion." (PMID 30718510, 2019). "Recent reports showed that CEMIP can suppress apoptosis via EGFR signaling as well as by enhancing glycogen breakdown to promote cancer cell survival." (PMID 31303964, 2019).